MYD88 (MYD88 innate immune signal transduction adaptor)
Diseases named in the same sentence as MYD88 in open-access papers (continued):
Sharing a sentence is not in itself a finding about the gene and the disease.
infection (continued). "IL-1β is a critical pro-inflammatory cytokine that is essential in response to infection and is thought to be induced mainly through the TLR/MyD88/NF-κB signaling pathway in monocytes/macrophages." (PMID 35928810, 2022). "After infection with Aeromonas hydrophila, we found that the IL-10 and IL-11 expression levels were upregulated in each group, while TLR-4, MYD88, and TNF-α were down regulated." (PMID 36139830, 2022). "Given that MyD88 is the key adaptor protein that leads to the activation of NF-κB and JNK signals during pathogen infection, we therefore determine the effect of PCV2 infection on bacterial infection in MyD88-deficient macrophages." (PMID 34394082, 2021). "Next, we overexpressed MyD88 by transfecting expression plasmid containing open reading frame of human MyD88 in HIV MDSC and measured the intracellular replication of M tuberculosis at 72-hrs post-infection." (PMID 33995365, 2021). "Mice lacking TRIF or TLR3 showed a lower CTL response and impaired viral clearance at the site of infection after HSV-1 flank infection, as compared with WT or MyD88−/- mice." (PMID 34895058, 2021). "Next, we infected C57BL/6 and MyD88-/- mice with MCMV and examined the expression of nutrient transporters on NK cells at D3 post-infection." (PMID 34093543, 2021). "NLRP3 inflammasome activation impaired agonist- or infection-induced TLR signaling and cytokine production through the proteolytic cleavage of MyD88 by caspase-1." (PMID 35069570, 2021). "During another H37Rv strain infection (200 CFU i.n.), Il1r1 KO mice phenocopied Myd88 KO mice (died around 4 weeks post infection)." (PMID 34276708, 2021). "Our results indicate MyD88-independent IL-12 production is both necessary and sufficient to drive IFN-γ production following infection." (PMID 34597344, 2021). "The Western blotting results show that TRIF and MAVS are most effective in inhibition, MyD88, RIPK2, CBM and STING are intermediate in inhibition, and ASC is barely effective in inhibition of N protein expression at 48 h and 72 h post infection of PRRSV." (PMID 34696285, 2021). "For instance, infection triggers co-expression of the cascade Toll-like receptor 5 (TLR5) and Myeloid differentiation primary response protein (MyD88), as previously reported in bony fish during bacterial infection." (PMID 33962693, 2021). "Apart from these orders, Rickettsiales were observed mainly in uninfected Myd88−/− and DKO mice as compared to TrifLps2 and WT mice and were almost lost upon infection with H. felis." (PMID 33477306, 2021). "Compatible with the behavior of the MyD88 KO, TLR2 and TLR5 proved important for both IL-6 and TNFα secretion following infection with L. pneumophila." (PMID 34280250, 2021). "Differentiated THP-1 macrophages (WT or MyD88 knockouts (KOs)) were infected with WT Mtb or PMM127 and treated with BafA1 to determine the total amount of LC3-II formed upon infection." (PMID 32182946, 2020). "For the TLR pathway, one TLR homolog, the adaptor molecule MyD88, TRAF6, kinase IRAK4 and two transcription factors IкB-α and NF-кB were all significantly upregulated after 6 h and 12 h of infection." (PMID 32276269, 2020). "Consistent with this, a knockout of MyD88 in THP-1 cells completely abolished the expression of the inflammatory cytokines TNF-α and IL-1β upon infection with C. acnes, L.m., or LPS." (PMID 33178195, 2020). "While there were some minor differences, we found overall that IL-12p40 production was very similar following infection with RH and Type II PTG in both MyD88+/+ and MyD88-/- BMDM." (PMID 32413093, 2020). "MyD88 levels and IKK-β, NF-κB (p65), and IκB-α phosphorylation in the jejunum increased significantly after infection with EHEC." (PMID 32695115, 2020). "The TLR4–/–and MyD88–/– mice survived less time after infection than their corresponding WT animals (WT.BL10 and WT.BL6, respectively), although the TLR4–/– mice survived worse than the MyD88–/– mice at this CFU dose." (PMID 33042124, 2020).
infection (continued). "In the current study, we demonstrate that the MyD88-dependent receptor TLR2 is critical for S. aureus containment in the brain and galea during craniotomy infection." (PMID 32290861, 2020). "The respiratory burst (ROS production) after infection was profoundly dampened in TLR4–/– and MyD88–/– mice." (PMID 33042124, 2020). "Both Myd88−/− and TLR7−/− mice exhibited higher viral loads than WT mice at late times post-infection." (PMID 30909385, 2019). "BeAn-infected SJL mice express several genes involved in the innate immune responses (Tlr7, Tlr8, Tlr9, Myd88, Isg15, Isg20, Mx1, and IL6) in the spinal cord during the late phase of TMEV-IDD at 165 days post infection." (PMID 30669615, 2019). "gga-miR-146c was functional by regulating TLR6/MyD88/NF-κB pathway and targeting MMP16 to manipulate cell cycle, multiplication, and apoptosis in host defense of MG-HS infection." (PMID 31137698, 2019). "In this study, the upregulation of MyD88, NF‐κB 52, and NF‐κB 65 in response to both GD and F48E9 infection was observed." (PMID 30070070, 2019). "In comparison to the control uninfected group, mRNA expression levels of TLR3, TLR4, TLR7, MyD88, RIG-1 and NF-κB p65 in the control infected group were prominently increased on days 3 and 7 post-infection (all P < 0.01)." (PMID 31551774, 2019). "This phenotype was confirmed after intratracheal infection with NMII, where an essential role of MyD88 in efficient elimination of NMII from the lung and from other tissues, including the heart, was observed." (PMID 30800124, 2019). "In accordance, even at a low dose of infection (equivalent to <1 LD50), MyD88−/− mice displayed high serum levels of anti-Salmonella antibodies of IgM as well as IgG3 and IgG2c and IgG1 isotypes in comparison to wild-type mice." (PMID 29973931, 2018). "Upregulation of TLRs, MyD88, TRAF, and IRAK occurs during head regeneration of S. mediterranea, indicating the TLR-initiated signaling pathway likely plays a role in preventing infection during the regeneration process." (PMID 30034391, 2018). "The infection of the high virulence type 1 RH strain of T. gondii induced the activation of p38 MAPK and IL-12 production via a MyD88-independent manner in BMDMs." (PMID 30452471, 2018). "The expression of MyD88, STAT1, and STAT2 increased after infection with both parasites day 1 and day 4 p.i." (PMID 30327482, 2018). "TLR-9 activation plays a primary role in MyD88 induction that is dependent on the synthesis of IL-12 and IFN-γ during T. cruzi experimental infection and contributes to the formation of a pro-inflammatory environment." (PMID 29599775, 2018). "Confocal immunofluorescence analysis showed that IOE infection of WT-BMM and MyD88-/- BMM significantly increased the percentage of cells with more than 5 LC3 puncta, as well as the number of LC3 puncta/cell when compared to uninfected counterparts." (PMID 29049365, 2017). "This is consistent with the data demonstrating that MyD88/TLR signaling is necessary for CXCL1 expression, which attracts neutrophils to the site of infection necessary for bacterial clearance." (PMID 28796783, 2017). "We show that functional MyD88 in IEC alone is indeed sufficient to upregulate RegIIIγ expression in IEC upon infection, confirming earlier reports that suggested an IEC-intrinsic role for MyD88 in regulating RegIIIγ expression." (PMID 28520792, 2017). "Abrogation of MyD88, the adaptor protein central to the TLR pathway, results in near complete lack of pro-inflammatory cytokine production in vitro following infection with S. suis." (PMID 28894449, 2017). "Using zebrafish Aeromonas hydrophila infection model, we demonstrate that synchronization of MyD88 and TRIF dependent pathways is critical for determining the fate of infection." (PMID 29142761, 2017).
infection (continued). "Together, these results for the first time demonstrated differential TLR4 signaling in course of A. hydrophila pathogenesis wherein MyD88 pathway is involved at the early stages and TRIF pathway at later stages of infection." (PMID 29142761, 2017). "In a murine model for RSV and influenza virus infection, OM-85 has been demonstrated to reduce the infection rate through Toll-like receptors (TLR) signalling, and TLR adaptors Trif and MyD88." (PMID 29182620, 2017). "IOE infection further increased the percentage of punctae and the number of LC3 puncta/cell in MyD88-/- BMM treated with Baf, which further confirm immunoblot data and suggest that MyD88 partially inhibits autophagic flux in IOE-infected BMM." (PMID 29049365, 2017). "WT, IL-1R-/-, and MyD88-/- mice were inoculated with 106 CFU GFP-PA01, following a corneal scratch wound, and clinical signs of infection evaluated by slit lamp examination after 24 hours." (PMID 28796783, 2017). "Our results showed that Myd88 located in lysosomes was increased by approximately 2-fold after infection with all the pathogen types, suggesting activation of the TLR-Myd88 pathway." (PMID 28088779, 2017). "brucei parasites penetrate the BBB very early during infection (within 2–3 days post infection), whereby they proposed that TLR9 and MyD88-mediated activation of DCs triggers via type-I IFN (IFN-α/β) T-cell activation." (PMID 27446070, 2016). "Several strains of mutant C57BL/6 mice (TCR-/-, C3-/-, CD16-/-, MyD88-/-, TRIF-/-, INFγ-/-, TNFR1-/-, Gal3-/-, Prf1-/-) with defects in innate and adaptive immunity were examined for expression of this infection-induced, immunosuppressive trait." (PMID 27403737, 2016). "Infection with P. aeruginosa triggered a strong innate immune response and a cytokine storm mediated by TLR and MyD88 signaling." (PMID 27982111, 2016). "Meanwhile, MyD88, LBP and TLR4 probably play an important role in stimulating immune and antigen presentation in piglet’s response to the infection of E. coli F18." (PMID 27809935, 2016). "Ly49H+ NK cells from BALB/c-Ly49H+ IFNAR-/- mice were significantly activated at d3 and d6 post infection, to levels similar to those observed in BALB/c-Ly49H+ MyD88-/- mice." (PMID 25954804, 2015). "Since an MOI of 100 and 1 h infection time resulted in a reasonable percentage of infected macrophages for analysis by FACS, wild type, TLR2-/- and MyD88-/- macrophages were infected with GFP expressing E99 (E99GFP) under these conditions." (PMID 26317438, 2015). "MyD88, an adaptor protein in the signaling pathway of TLR, seems to be very important for the secretion of IL-1α by mouse peritoneal macrophages following infection by L. major." (PMID 26107286, 2015). "Our results show that MyD88 proinflammatory cytokines (TNF-α and IL-1β) and transcriptional and translational products, increase after infection." (PMID 26021751, 2015). "Host defense against A. fumigatus involves the activation of two host signal transducers, MyD88 and CARD9, leading to neutrophil recruitment to the infection site." (PMID 25621893, 2015). "To better understand the therapeutic mechanism of MJWQH in mice infected with H1N1 virus, we measured the expressions of TLR7, MyD88, TRAF6, p65, p-p65, IκB-α, and p-IKKα/β in lung tissues on days 2 and 4 after infection by using Western blot analysis." (PMID 26089947, 2015). "At d4 post infection, BALB/c MyD88-/- and BALB/c IFNAR-/- mice also harbored a marked disruption of their spleen architecture." (PMID 25954804, 2015). "MyD88(−/−)CARD9(−/−) mice rapidly and universally succumbed to this infectious inoculum, while the mice in all other groups survived the infection." (PMID 25621893, 2015). "West Nile virus (WNV) vaccination studies revealed that MyD88 and TLR3 are both required for efficient humoral immune responses, and during a WNV infection Rig-I and MDA5, as well as TLR3 and TLR7 are involved in immune recognition." (PMID 25539593, 2014).
infection (continued). "The magnitude of Vγ1+ T cell expansion in MyD88−/− or TLR7−/− mice was reduced at day 3 and remained lower in MyD88−/− mice at day 5 post-infection (P<0.05 or P<0.01)." (PMID 25232836, 2014). "Fibrate-treatment resulted in down-regulation of MyD88 and TNF-α expression at 1 and 6 h after infection in U937 cells." (PMID 25299393, 2014). "TLR4 is capable of inducing type I interferon production via either MYD88 or the alternative adapter TRIF, but infection of Tlr2/Tlr4 double knock-out cells induced antiviral gene expression, ruling out a role for TLR4 as well." (PMID 24505488, 2014). "MyD88 is a messenger of TLR signaling during a TB infection and TNF-α is important in the macrophage infection mechanism via TB phagocytosis." (PMID 25299393, 2014). "Thirty-nine viral genes and five host genes including MyD88, IFI44, IkB2, IAP and Gly were measured at 0.5, 10, 26, 72 and 144 hours post infection (hpi)." (PMID 25294338, 2014). "For this purpose we evaluated the expression of TLR-2, MyD88, IRAK4, TRAF6, and TIRAP in macrophages at 48 hr after infection with H37Rv, BCG, H37RvΔRD-1 or H37RvΔESAT-6." (PMID 24475192, 2014). "It will be important, however, for future work to examine whether a lack of IL-18 recapitulates the heightened resistance of MyD88−/− mice, as during infection with T. muris, IL-18 has been shown to promote susceptibility to infection through the inhibition of Th2 cytokines." (PMID 25114104, 2014). "This strategy delays the development of protective host responses to infection, by relying on cell types other than IEC to drive protective host (MyD88) responses to infection." (PMID 23950714, 2013). "The expression of MyD88, TLR9 and TLR7 (recently demonstrated as mediating the pDC response to LCMV) increased during LCMV-WE infection but only enabled infant pDCs to reach the levels observed at baseline in adult pDCs." (PMID 24376875, 2013). "Innate immune signaling molecules such as TLR, NOD, MyD88, and pro-inflammatory cytokines such as IFN-γ and TNF-α play key roles in regulating control of infection." (PMID 23508691, 2013). "After confirming overexpression of MyD88 and Mal in HCE cells, we co-transfected the NF-kB reporter plasmid together with TLR4/MD2, Mal/MyD88 and measured luciferase activity at 4 h after HSV-2 infection or mock-infection." (PMID 24278275, 2013). "After intraperitoneal amastigotes inoculation in wild-type and knockout mice for TNF-α, Nod2, Myd88, iNOS, IL-12p40, IL-18, CD4, CD8 and IFN-γ we found that the latter is crucial for controlling infection by G strain amastigotes." (PMID 22509418, 2012). "Another unexpected observation in this study was the delay in infection of the spleens and livers of TLR4−/− and MyD88−/− mice 1–2 weeks post-inoculation." (PMID 22973560, 2012). "Cleavage of caspase-7 during L. monocytogenes infection did not require caspase-1 or key adaptors of the primary pathways of innate immune signaling in this infection, ASC, RIP2 and MyD88." (PMID 22807671, 2012). "The change pattern of transcription levels of MyD88, IRAK-1, and TRAF-6 of macrophage was consistent with its response to pRBC lysate after infection with either strain." (PMID 22463100, 2012). "Based on the histological appearance of the liver lesions that we found in Myd88-IFNAR double-KO mice, the primary etiologic possibilities for these findings are infections, ischemia, and toxins." (PMID 22216024, 2011). "We also demonstrate the significance of TLR4 in murine infection with C. difficile, with TLR4−/− and MyD88−/− mice displaying a more severe infection than wild type." (PMID 21738466, 2011). "Total number of PMN and NK cells after infection with Vi+ or Vi−S. Typhimurium in TLR4−/− and MyD88−/− mice." (PMID 21829346, 2011). "Analysis of MyD88−/−, TRIF−/−, TLR4−/−, and TLR9−/− mice revealed that TLR4- and TLR9-signaling was essential for immunopathology following C. jejuni-infection." (PMID 21698299, 2011).
infection (continued). "In contrast, although the response to SGB1 Vi− infection in TLR4−/− and MyD88−/− was reduced compared to that in WT mice, there was still a significant response compared to naïve mice." (PMID 21829346, 2011). "In Myd88−/− mice, essential chemokine and neutrophil responses to CFT073 infection were completely abrogated consistent with the importance of MyD88 for the overall innate immune response to these infections." (PMID 20886104, 2010). "After 3 days of infection with MHV-68, both WT and TLR2−/− mice secreted similar IL-6 levels in the lung tissue, while MyD88−/− mice showed reduced IL-6 lung concentrations." (PMID 21060793, 2010). "Second, the higher susceptibility of Myd88−/− mice could be directly attributed to the defective activation of CD4+ T cells demonstrated here, as this cell population has also been demonstrated to be essential for resistance to infection, probably through IFN-γ and TNF-α secretion." (PMID 20442858, 2010). "One hour after infection of WT BMM with Mp, NFκB had largely translocated into the nuclear compartment, whereas it remained in the cytoplasm in BMM from MyD88−/− mice." (PMID 21203444, 2010). "al. identified a role for Myd88, an adapter protein of TLR signaling, and RAG1, necessary for antibody production, in protection from infection and disease." (PMID 20386712, 2010). "C57BL/6, MyD88−/−, TIRAP−/− and TRIF−/− mice were injected intrastromally with Af293.1RFP conidia, and markers of infection were examined as before." (PMID 20617171, 2010). "Thus, the documented high susceptibility of Myd88−/− mice to infection with T. cruzi could not be attributed to a single TLR, suggesting that different members of the TLR family act in concert in determining resistance to the pathogen." (PMID 20442858, 2010). "Interestingly, MyD88 may play an essential role only during the early phase of infection (4-8 hours) as inflammation and control of bacterial load 48 hours after low dose infection occurred through an undetermined MyD88-independent mechanism." (PMID 21108806, 2010). "Our results indicate that during acute infection with MHV-68, TLR2 signaling via MyD88 is an important aspect of the proinflammatory and antiviral responses directed against this virus." (PMID 21060793, 2010). "Before infection with Mp or mock infection, BMM from WT or MyD88−/− mice have similar low levels of activated NFκB in the total cell extracts." (PMID 21203444, 2010). "According to this hypothesis, cytotoxic CD8+ T cells would not be preserved in doubly deficient Myd88−/−Trif−/− mice, which is in agreement with the fact that these mice are even more susceptible to infection, as indicated by accelerated mortality when compared to single Myd88−/− mice." (PMID 20442858, 2010). "In blood, plasmacytoid DC (pDC) are believed to be primary producers of type I IFN during infection by RNA viruses; in pDC, IFN is induced after nucleic acid recognition by TLR7 and signaling through MyD88 to IRF-7." (PMID 19798431, 2009). "Four hours post infection, serum IL-10 was detectable in mice immunized with LLO-Lm-OVA, either alone or in combination with ActA-Lm-OVA, and required the adapter protein MyD88." (PMID 19730694, 2009). "Primary macrophages from MyD88−/− and TLR2−/− mice were significantly impaired in the ability to secrete TNF and other pro-inflammatory cytokines upon ex vivo infection with LVS." (PMID 19936231, 2009). "Infection with HPV 16L1 virus-like particles (VLPs) provides immunity by activating DCs and a potent neutralizing IgG response, which requires MyD88-dependent signaling." (PMID 19088911, 2008). "In contrast, infection with LT2 upregulated MD2, CD14, MyD88, and TRIF mRNA expression." (PMID 41474380, 2026).